GSK3B (glycogen synthase kinase 3 beta)
Diseases named in the same sentence as GSK3B in open-access papers (continued):
Sharing a sentence is not in itself a finding about the gene and the disease.
glioma (continued). "To further explore the pathway through which miR-29a/b/c suppress glioma cell proliferation, we focused on the crucial effectors downstream of TRAF4, including AKT, GSK-3β, c-Myc, and the G1/S-phase checkpoint regulator cyclin D1." (PMID 30348972, 2018). "Based on these findings, we conclude that miR-29a/b/c suppress G1/S-phase transition and the proliferation of glioma cells by targeting TRAF4 and down-modulating the AKT/GSK-3β pathway." (PMID 30348972, 2018). "Moreover, in the present study, changes in mTOR/p70S6K1 signaling pathway occurred in U87 and U251 glioma cells following GSK-3β overexpression, suggesting that this signaling pathway may play an important role in the GSK-3β-inhibited glioma development events." (PMID 26388612, 2015). "We further analyzed the expression levels of GSK-3β and p-GSK-3β (Ser9) in 5 normal brain tissues and 33 glioma specimens by Western blotting assay." (PMID 26388612, 2015). "The expression levels of GSK-3β and p-GSK-3β (Ser9) in 9 normal tissue specimens and 90 glioma tissues of paraffin-embedded formalin-fixed were detected by Tissue Microarray Analysis (TMA)." (PMID 26388612, 2015). "More importantly, forced expression of miR-135b into GSCs markedly suppressed proliferation, motility and invasion of glioma cells as well as their stem cell-like phenotype through targeting ADAM12, SMAD5 and GSK3β." (PMID 26437223, 2015). "In this study, we screened a diverse range of chemically distinct small molecule inhibitors of GSK-3β, PDE7 and/or dual GSK-3β/PDE7 in a Drosophila melanogaster glioma model with the objective of identifying the most promising candidates for future translational studies." (PMID 40157890, 2025). "Taken together, these results suggest that IFI30‐mediated EGFR/AKT/GSK3β/β‐catenin signaling not only promotes the EMT‐like phenotype by up‐regulating the expression of Slug, but also subsequently enhanced invasion and chemoresistance of glioma cells." (PMID 37408388, 2023). "Although not validated in primary cells, we previously reported that glycogen synthase-kinase 3-beta (GSK3b) regulates mitochondrial energy metabolism via PGC-1a in glioma cells (H4) and in phaeochromocytoma-differentiated neurons (PC12)." (PMID 37808866, 2023). "Because the Wnt/β-catenin signaling pathway is usually active in the glioma, we investigated whether miR-640 inhibition and SLIT1 silencing affect GSK-3β, Wnt, or β-catenin expression." (PMID 35996510, 2022). "Although it plays an important role in tumors, the mechanism and regulatory network of GSK3β in gliomas have not been elucidated." (PMID 35606353, 2022). "NEAT1 may interact with EZH2 and mediate H3K27 trimethylation in their promoters, and NEAT1 was essential for glioma cell proliferation and invasion, since it increased β-catenin nuclear transport while decreasing ICAT, GSK3B, and Axin2 expression." (PMID 37305396, 2021). "Lower grade gliomas, the AA group, harbored the highest number of CNA in genes PTEN (50%), PIK3AP1 (49%), and CHUK (49%), while the DA group carried the highest number of CNA in genes AKT1 (15%), AKT2 (11%), and GSK3β (11%)." (PMID 34209611, 2021). "While overexpression FTL in glioma cells increased p-AKT (ser473) and p-GSK3β(ser9)." (PMID 32677981, 2020). "Moreover, NEAT1 was critical for glioma cell growth and invasion by increasing β-catenin nuclear transport and down-regulating ICAT, GSK3B, and Axin2." (PMID 32443824, 2020). "(A&B) Representative immunoblots of GSK-3β, p-GSK-3β, β-catenin, active-β-catenin and p-β-catenin after over-expression of YAP or YAP S94A in U251 (A) and U87 (B) glioma cells.The results indicate that YAP S94A recapitulated the effect of YAP wild type on GSK3β and β-catenin phosphorylation." (PMID 28962630, 2017).
glioma (continued). "In addition, the inhibition of JNK suppresses the activation of Akt and its downstream mediators, GSK-3β and Bad, but potentiates TMZ-induced cytotoxicity in U87 glioma cells." (PMID 27074557, 2016). "The levels of p-GSK-3β (Ser9), but not total GSK-3β, are significantly up-regulated in glioma tissues compared to normal tissues, and are significantly correlated with the glioma grades." (PMID 26388612, 2015). "Thus we investigated the possible effects of SR141716 on modulating GSK-3β and STAT3 activity in our experimental model starting from U251 glioma cell lines, while confirming it in high- and low-CB1-expressing primary cells." (PMID 26008966, 2015). "Interestingly, we found that MAZ51 activated Akt and increased the phosphorylation of GSK3β at position Ser9, which represents the inactive form of GSK3β; this suggests that Akt-mediated inhibition of GSK3β may contribute to the cytoskeletal alterations in glioma cells induced by MAZ51." (PMID 25268128, 2014). "Most importantly, this GSK3β-mediated radioprotection does not occur in glioma cells examined in the studies." (PMID 23388100, 2013). "We therefore investigated whether localized GSK-3β, a subtype of GSK-3, is important for glioma cell invasion." (PMID 24312592, 2013). "When glioma cells stimulated with serum or EGF, GSK-3β was regulated through its localized inhibition, characterized by the increased phosphorylation at the Ser9 of GSK-3β (pSer9-GSK-3β) at the leading edge of migrating glioma cells." (PMID 24312592, 2013). "Although previous studies have revealed that GSK-3β is critical for polarity formation of neurons and glia, its role in glioma invasion was not clear." (PMID 24312592, 2013). "Evaluation of CDC2 and GSK3β activation states in infiltrative primary glial tumors of other lineages has not been thoroughly evaluated." (PMID 21660227, 2011). "Indeed, our interrogation of publicly available patient expression data from LGG patients confirmed a positive correlation between L1CAM and the predominant isoform GSK3B in IDHmut gliomas (source: CGGA) and showed that GSK3B is significantly upregulated in IDHmut glioma patients (source: CGGA)." (PMID 40307935, 2025). "For example, GSK-3β is classically recognized as a tumor suppressor in a variety of tumors, whereas GSK-3β is considered an oncogene and actually promotes the development of several other cancer types, including mixed lineage leukemia 37, 38, glioma 39, osteosarcoma 40, and oral cancer." (PMID 32754263, 2020). "Additionally, it was shown that major cWnt signaling molecules, such as β-catenin and GSK3β are not expressed in glioma cells highlighting the possibility of other pathways driving glioma progression." (PMID 30510501, 2018). "Here, our data revealed that knockdown of PLOD2 resulted in decreased level of p-PI3K, p-AKT, p-GSK-3β and β-catenin, implicating that inactivated PI3K/AKT signaling may be responsible for shPLOD2-mediated suppression of glioma cell proliferation, migration and invasion." (PMID 28410212, 2017). "Moreover, MYH9 interacted with GSK-3β to inhibit the expression of GSK-3β protein by promoting its ubiquitination; the downregulation of GSK-3β subsequently promoted the nuclear translocation of β-catenin, enhancing growth, invasion, migration, and temozolomide resistance in glioma cells." (PMID 34887392, 2021). "Consistent with the results in TMA, the expression levels of p-GSK-3β (Ser9), but not total GSK-3β, were greatly increased in glioma tissues, and were positively correlated with higher glioma grades." (PMID 26388612, 2015). "While most gliomas demonstrate markedly decreased GSK3β function, lithium or SB216763 will not be able to generate significant modification in GSK3β-NHEJ activity as in normal neuronal cells." (PMID 23388100, 2013).
prostate carcinoma (146 papers, 2009 to 2026). A carcinoma that arises from epithelial cells of the prostate gland. "This interaction leads to a reduction in the activation of the associated epithelial–mesenchymal transition and promotes prostate cancer through GSK3β/β-catenin signaling." (PMID 39550407, 2024). "The mutation of various phosphorylation sites in GSK3B was identified in cell nuclei of prostate cancer tissue samples and contributed to prostate cancer progression by increasing protein kinase B/Akt and Akt activity." (PMID 35242279, 2022). "Further investigations with different systems biology methods have prioritized NR3C1, ABHD2, and GSK3B as potential genes involved in prostate cancer metastasis owing to their high mutation load and expression status." (PMID 36468011, 2022). "GSK-3β activation has been associated with prostate cancer progression and TDZD-8 has an inhibitory effect in these tumor cells." (PMID 21079728, 2010). "Understanding GSK3β regulation by the Akt pathway is important to the present study because a PTEN mutation in PC-3 prostate cancer cells results in activated Akt, GSK3β inhibition, and activation of endogenous β-catenin." (PMID 19274078, 2009). "Additionally, the high cytoplasmic expression of GSK3β is associated with high-risk prostate cancer cases." (PMID 40072085, 2025). "Thus, identifying a signaling target linked to lipid metabolism downstream of GSK3β inhibition could be insightful for uncovering the mechanism by which PIM1 mediates LD accumulation in prostate cancer." (PMID 38097734, 2024). "This may underlie the dramatic effects of GSK-3β inhibition on prostate cancer migration." (PMID 25344861, 2014). "Our studies show for the first time that GSK3β is inhibited following IL-24 treatment in human prostate cancer cells." (PMID 40072085, 2025). "This study focuses on GSK3β due to its emerging potential as a therapeutic target in prostate cancer." (PMID 40072085, 2025). "The requirement for GSK3β phosphorylation in serine 9 for IL-24-induced apoptosis was analyzed by IL-24 treatment of human prostate cancer cell lines expressing constitutively active GSK3β." (PMID 40072085, 2025). "Subsequent research should aim to precisely delineate the most effective combinations of IL-24 as a GSK3β inhibitor with cytotoxic agents in different cancers, including prostate cancer cells." (PMID 40072085, 2025). "While β-catenin has been shown to interact with the androgen receptor (AR), the key driver of prostate cancer, extensive studies indicate that GSK3β positively regulates AR activation and promotes tumor progression independently of Wnt signaling." (PMID 40072085, 2025). "The findings of this study uncover a novel mechanism of IL-24 in apoptosis mediated through cAMP/PKA/GSK3β regulation in prostate cancer cells." (PMID 40072085, 2025). "This choice was influenced by the literature considering GSK3β a promising target for prostate cancer research and potential therapeutic development." (PMID 40072085, 2025). "We treated DU145 human prostate cancer cells with increasing concentrations of IL-24 for 72 h and analyzed the activity and phosphorylation of serine 9 of GSK3β." (PMID 40072085, 2025). "Based on these findings, we proposed a model whereby PIM1 drives LD accumulation by phosphorylating and inhibiting GSK3β in prostate cancer." (PMID 38097734, 2024). "In prostate cancer cells, melatonin inhibits the phosphorylation of both Akt and its target GSK-3β, indicating that the pineal hormone inhibits the migration and invasion of PCa cells, at least in part, by suppressing the AKT/GSK-3β-mediated EMT." (PMID 38473317, 2024). "The phosphorylation of GSK3β Ser9 site by PIM1 kinase inhibits GSK3β activity, thereby promoting the migration and invasion of prostate cancer cells." (PMID 39227379, 2024). "Taken together, these data indicate that PIM1 amplifies peroxisomal biogenesis by inhibiting GSK3β-PPARα signaling to induce LD accumulation in prostate cancer." (PMID 38097734, 2024).
prostate carcinoma (continued). "Collectively, the results indicate that PIM1 regulates LD accumulation in prostate cancer by inhibitory phosphorylation of GSK3β at S9." (PMID 38097734, 2024). "Mechanically, TPX2 mediates prostate cancer EMT through cyclin-dependent kinase (CDK1)-regulated phosphorylation of ERK/GSK3β/SNAIL pathway." (PMID 36707511, 2023). "DANCR can also target miR-185-5p to increase expression of LIM and SH3 protein 1 promoting prostate cancer through the FAK/PI3K/AKT/GSK3β/snail axis." (PMID 37025585, 2023). "Human tubulin beta class IVa (TUBB4A) interacts with MYH9 to protect against nuclear DNA damage and promotes cell EMT and migration via activation of GSK3β/β-catenin signalling in prostate cancer." (PMID 37875476, 2023). "For instance, it is responsible for prostate cancer migration and proliferation and can regulate Akt/GSK3-β pathway activity 9,27." (PMID 36147460, 2022). "miR-218b targeting of Gab2 mediates the tumorigenesis in prostate cancer through the PI3K/AKT/GSK-3β pathway." (PMID 36421826, 2022). "The GSK3B is targeted by lithium carbonate inhibitor which currently completed phase 1 trial in prostate cancer." (PMID 36468011, 2022). "In prostate cancer, IL-8 activates the mTOR signaling pathway to defend prostate cancer cells against the oxidative damage induced by GSK-3β." (PMID 36428665, 2022). "In this regard, one of the most common regulatory mechanisms is the phosphorylation of Snail by glycogen synthase kinase 3 beta (GSK-3β), which induces its nuclear export to cytosol and marks this protein for degradation in prostate cancer." (PMID 33800291, 2021). "In LnCAP prostate cancer cells, TRPM4-associated Ca2+ influx stimulates AKT1, which in turn increases the inhibitory Ser9 phosphorylation of GSK3β and the total amount of β-catenin." (PMID 33117152, 2020). "In this scenario, GSK-3α and GSK-3β were acting as tumor promoters and their suppression eliminated the growth of drug-resistant prostate cancer cells." (PMID 32365809, 2020). "miR-425-5p as a tumor suppressor gene is low expressed in prostate cancer and can affect the sensitivity of prostate cancer to cisplatin through the action of GSK3β and Wnt/β-catenin signaling pathways." (PMID 33123581, 2020). "In prostate cancer cells, inhibition of GSK3β promotes autophagy activity by the LKB1-AMPK pathway, in parallel with an increased protein level of LC-3B, and p62 protein reduction." (PMID 31683987, 2019). "Kenpaullone has been reported to have therapeutic potential for several cancer types such as breast and prostate cancers via inhibition of GSK3β and CDK12,22–26." (PMID 31296906, 2019). "The WNT genes showed crosstalk with Wnt/GSK-3β signaling pathways where WNT genes marked as potent genes interconnected within pathways in prostate cancer, imprints the effect on cancer stem cell proliferation, migration and differentiation." (PMID 30972102, 2019). "This study presents further evidence to show that TRPM4 regulates β‐catenin signaling and enhances the proliferation of prostate cancer cell lines, through a calcium‐dependent regulation of Akt1 and GSK‐3β activity." (PMID 28614631, 2018). "bFGF has been shown to promote phosphorylation of AKT and GSK-3β in the prostate cancer cell line PC-3." (PMID 29262637, 2017). "The same effect was observed in LNCaP prostate cancer cells following GSK3β-K85R transfection, and was corroborated by a 50% reduction in levels of the same mature miRs following 99021 treatment of LNCaP cells." (PMID 27907888, 2017). "During cancer metastasis, bFGF was also shown to induce EMT through the AKT/GSK-3β/Snail signalling pathway, resulting in the promotion of migration and invasion of prostate cancer cells." (PMID 29262637, 2017). "There is also a strong evidence supporting a role of GSK3β in prostate cancer where it is involved in promoting androgen receptor function and nuclear translocation." (PMID 27602497, 2016).
prostate carcinoma (continued). "A close connection of GSK3β in prostate cancer has been demonstrated earlier by the fact that increased cytoplasmic GSK3β correlated with the clinical stage and Gleason score in prostate tumor samples." (PMID 27602497, 2016). "Despite these confirmations, two most recent reports emanating from the same laboratory argues the effect of GSK3β activation on EMT in prostate cancer." (PMID 25714023, 2015). "In conclusion, these findings suggest that inhibition of Akt signaling and activation of GSK-3β partially contributes to the pro-apoptotic effect of embelin in prostate cancer cells." (PMID 26252009, 2015). "The present study shows that embelin induces mitochondrial-dependent apoptosis and suppression of β-catenin expression via Akt inhibition and GSK-3β activation in human prostate cancer cells." (PMID 26252009, 2015). "This was in agreement with the clinical report from human prostate cancer patient tumor tissues indicating increased protein and mRNA expression of GSK3α starting from the early tumor growth and increased expression of GSK3β specifically in advanced cancers." (PMID 25714023, 2015). "This indicated that in prostate cancer cells, GSK3β inhibition will lead to stabilization of cell-barrier inhibiting cell scattering and reversing EMT." (PMID 25714023, 2015). "Phosphorylation of the androgen receptor (AR) hinge and ligand-binding sites by GSK3β has been reported to inhibit expression of AR gene targets, thus inhibiting androgen-dependent prostate cancer cell proliferation." (PMID 25714023, 2015). "ShRNA-mediated knockdown of GSK3α and GSK3β equally inhibited the ability of prostate cancer cells to migrate and invade the endothelial-barrier in vitro, and PC3 cell micrometastasis to lungs in vivo." (PMID 25714023, 2015). "Overall, our data demonstrated the isoform specific role of GSK3α and GSK3β in prostate cancer cells in vitro, and tumor growth and micrometastasis in vivo, via distinct molecular and cellular mechanisms." (PMID 25714023, 2015). "Nevertheless, we provide the first report on the isoform specific function of GSK3α and GSK3β in the regulation of prostate cancer cell survival and proliferation, as well as EMT and micrometastasis, respectively." (PMID 25714023, 2015). "Together, these results indicated that both GSK3α and GSK3β isoforms are necessary for the prostate cancer cell motility and invasion." (PMID 25714023, 2015). "A number of reports since mid-2000 have also revealed GSK3β as a prostate cancer promoter, further demonstrating the importance of GSK3β in prostate cancer." (PMID 25714023, 2015). "Other groups previously reported that DAB2IP suppressed EMT by modulating GSK3β/β-catenin signaling pathway in prostate cancer." (PMID 26336990, 2015). "This suggested distinct roles for GSK3α and GSK3β in the early and later stages of prostate cancer growth." (PMID 25714023, 2015). "Analyses of prostate cancer patient samples have demonstrated a positive correlation between increased levels of cytoplasmic GSK-3β, clinical stage and Gleason score." (PMID 24519956, 2014). "Overexpression of talin in prostate cancer cells induced phosporylation of Akt and GSK-3β, thus leading to enhanced survival and resistance to the action of DZ-50." (PMID 24497940, 2014). "We show that GSK-3β provides a potential therapeutic target that is functionally involved in prostate cancer stem cell maintenance, tumorigenicity and metastasis in vivo." (PMID 25344861, 2014). "Taken together, our mechanistic observations highlight the importance of GSK-3β activity in the maintenance of prostate cancer stem/progenitor-like cells and prostate cancer progression in vivo." (PMID 25344861, 2014). "In this study, we established the role of GSK-3β in the acquisition and maintenance of an invasive, tumorigenic and metastatic phenotype in human prostate cancer cells using a selective, small molecule inhibitor of GSK-3β." (PMID 25344861, 2014).